CHEK2 (checkpoint kinase 2)
Diseases named in the same sentence as CHEK2 in open-access papers (continued):
Sharing a sentence is not in itself a finding about the gene and the disease.
ovarian cystadenoma (3 papers, 2020 to 2022). A benign ovarian surface epithelial-stromal tumor characterized by the presence of cystic structures lined by serous epithelial cells, mucinous columnar epithelial cells, or endometrial-type well-differentiated cells. "In the literature, we found information indicating that positive associations were seen with the CHEK2 I157T missense variant and ovarian cystadenomas (OR = 1.7; p = 0.005), borderline ovarian cancers (OR = 2.6; p = 0.002), and low-grade invasive cancers (OR = 2.1; p = 0.04)." (PMID 32570972, 2020).
testicular germ cell tumor (3 papers, 2021 to 2023). A germ cell tumor arising from the testis. "Recently, a multicenter case-control analysis using WES provided evidence for germline CHEK2 LOF variants as new moderate-penetrance variants in testicular germ cell tumors." (PMID 34549727, 2021). "Indeed, CHEK2 has been associated with an increased risk for testicular germ-cell tumors, breast cancer, and colorectal cancers." (PMID 36360192, 2022).
uveal melanoma (3 papers, 2015 to 2025). A melanoma derived from melanocytes of the uveal tract. "In this short report, we retrospectively analyzed and reported 10 metastatic uveal melanoma (MUM) patients with CHEK2 variants among 740 MUM cases (1.4%) in our MUM database and Caris database." (PMID 40283643, 2025). "In addition to patients with UM metastasis, our database contained four primary uveal melanoma patients with CHEK2 germline mutations." (PMID 40283643, 2025). "Since we have not tested all primary uveal melanoma patients with germline CHEK2 variations, we do not know the incidence of CHEK2 variation in the general population of primary uveal melanoma patients." (PMID 40283643, 2025).
acute leukemia (2 papers, 2018 to 2024). A clonal (malignant) hematopoietic disorder with an acute onset, affecting the bone marrow and the peripheral blood.
acute promyelocytic leukemia (2 papers, 2016 to 2021). An aggressive form of acute myeloid leukemia (AML), characterized by arrest of leukocyte differentiation at the promyelocyte stage, due to a specific chromosomal translocation t(15;17) in myeloid cells. "CHEK2 phosphorylates PML (Promyelocytic Leukemia) and appears to require PML for subsequent autophosphorylation." (PMID 26732650, 2016).
adenoma (2 papers, 2021). A neoplasm arising from the epithelium. "The patient with a CHEK2 mutation underwent his first colonoscopy at age 40 due to hematochezia where he had three tubular adenomas removed (12, 15 and 30 mm)." (PMID 33436027, 2021). "Similarly, we cannot presume that the CHEK2 variant caused the three advanced adenomas found in our second patient." (PMID 33436027, 2021). "However, IHC staining of Chk2 in the adenoma tissues of 3 CHEK2 variant carriers including individual II-1 revealed nuclear expression of the protein." (PMID 34549727, 2021). "In our study, we found APC somatic mutations in adenomas of CHEK2 mutant carriers." (PMID 34549727, 2021).
astrocytoma (2 papers, 2021 to 2026).
colorectal adenocarcinoma (2 papers, 2021 to 2024). The most common type of colorectal carcinoma. "The patient’s genetic profile, including a CHEK2 mutation, HER-2 positivity, and a KRAS mutation, significantly impacts the behavior of colorectal adenocarcinoma and its response to treatment." (PMID 39221315, 2024).
colorectal polyp (2 papers, 2020 to 2022). "One frameshift mutation in BRCA2 and one frameshift mutation in the CHEK2 gene were found in a normal control and two colorectal polyp patients, respectively." (PMID 33260537, 2020).
hemangioblastoma (2 papers, 2016 to 2019). "In this study, we have demonstrated in two different tumor cohorts and using two different techniques for copy number alteration detection, SNP and digital PCR, that Chek2 is deleted and EGFR, PTPN11, Ptch1 amplified in majority of hemangioblastoma patients." (PMID 26768750, 2016).
Infertility (2 papers, 2017 to 2024). "Two loci were associated with early-onset infertility (diagnosed before age 30), located near CHEK2 and within the major histocompatibility complex (MHC) region." (PMID 39566493, 2024). "To further investigate the relationship between CHEK2, PCOS, and infertility, we conducted follow-up analyses." (PMID 39566493, 2024).
oesophageal cancer (2 papers, 2004 to 2024).
oligodendroglioma (2 papers, 2022 to 2026). A well-differentiated (WHO grade II), diffusely infiltrating neuroglial tumor, typically located in the cerebral hemispheres. "Herein, we reported a p.R137* mutation that occurred in the CHEK2 FHA domain in a Chinese female patient with oligodendroglioma for the first time." (PMID 35281821, 2022). "Case presentation: A case of an oligodendroglioma patient harboring the germline CHEK2 p.R137* mutation was reported." (PMID 35281821, 2022). "Given the absence of other known genetic predisposing risk factors, we considered that oligodendroglioma might be associated with the CHEK2 mutation." (PMID 35281821, 2022). "Therefore, further studies are needed to confirm the association between the CHEK2 gene and oligodendroglioma." (PMID 35281821, 2022).
osteomyelitis (2 papers, 2024 to 2025). An acute or chronic inflammation of the bone and its structures due to infection with pyogenic bacteria. "This study delineates MEK1 signaling in macrophages as a central regulator of S. aureus-induced osteomyelitis, orchestrating mitophagy and host defenses through the epigenetic control of CHEK2." (PMID 40437411, 2025). "Together, our findings indicate that S. aureus infection may activate EGFR-MEK1/2 signaling, thereby suppressing mitochondrial ROS levels by downregulating Chek2 expression, leading to the progression of S. aureus osteomyelitis in mice." (PMID 39102432, 2024).
pituitary adenoma (2 papers, 2022 to 2026). "Potential associations include variants in emerging pituitary adenoma predisposition genes, including NF1, PRKACB, PAM, and CHEK2." (PMID 41965096, 2026). "Although pituitary adenomas, PNETs, and PCC have been associated with NF1 gene mutations, the second sister with a PCC did have proven germline CHEK2 with a pathogenic somatic NF1 mutation." (PMID 36440216, 2022). "Here we describe a patient with a history of colon polyps, pituitary adenoma, PNET, and a CHEK2 c.1100delC germline mutation." (PMID 36440216, 2022). "Due to patient’s history of pituitary adenoma and PNET, she underwent genetic testing, which revealed CHEK2 c.1100delC, and no other susceptibility mutation was identified." (PMID 36440216, 2022).
polyposis (2 papers, 2022 to 2025). "Of note, neither RNF43 nor CHEK2 is included in the current UK Cancer Genetics Group panel testing for polyposis patients." (PMID 35128723, 2022).
prostate tumor (2 papers, 2015 to 2021). "The CHEK2 p.R180C variant was also previously reported in 2.1% (2/94) prostate tumor samples of Caucasian American patients who were diagnosed before the age of 59 and in germline DNA of 1/423 (0.24%) unaffected men." (PMID 25629968, 2015).
thyroid nodule (2 papers, 2019 to 2024). A small circumscribed mass in the THYROID GLAND that can be of neoplastic growth or non-neoplastic abnormality. "Some of the identified variants in the CHEK2 gene are pathogenic or likely pathogenic and the influence of found variants in the IDH1 and PPM1D gene on thyroid nodules is still uncertain and probably benign." (PMID 31085772, 2019). "Segregation analysis in Family F83 showed that the CHEK2 variant segregated with TC, thyroid FND, and no otherwise specified thyroid nodule(s) (NOS-TN) in the family." (PMID 38367672, 2024).
urothelial bladder cancer (2 papers, 2021). "In 2008, we studied 416 unselected cases of urothelial bladder cancer for CHEK2 mutations which revealed a frequency of 10.6% (OR 1.9; p = 0.0003)." (PMID 34499690, 2021).
acral melanoma (1 paper, 2020). "The driver mutations in the genes RICTOR, CDK4, PDGFRA, KIT were specific for acral melanoma, while the amplification or deletion of the genes CCND2 and CHEK2 are uniquely found in mucosal melanoma." (PMID 32825510, 2020).
Adult onset (1 paper, 2024). Onset of disease manifestations in adulthood, defined here as at the age of 16 years or later. "The other P/LP variants are associated with adult-onset tumor predisposition syndromes, of which BRCA2 and CHEK2 in particular have relevance in terms of surveillance for the index patients and relatives." (PMID 38415346, 2024).
anaplastic thyroid cancer (1 paper, 2022). "A case-control study of patients with non-anaplastic thyroid cancer in an Iranian population found no germline CHEK2 mutations in cases nor controls, though this probably reflects the low frequency of CHEK2 mutations in the Middle Eastern population." (PMID 35101071, 2022).
Anxiety (1 paper, 2021). Intense feelings of nervousness, tension, or panic often arise in response to interpersonal stresses. "Our findings suggest that the women recontacted for additional genetic testing appreciated our effort and that the written information was sufficient to make an informed decision about the additional CHEK2 testing regardless of the test result and the possible anxiety it caused." (PMID 33468213, 2021).
Ataxia (1 paper, 2020). Ataxia refers to impaired coordination of voluntary muscle movement.
Beckwith-Wiedemann syndrome (1 paper, 2025). Beckwith-Wiedemann syndrome (BWS) is a genetic disorder characterized by overgrowth, tumor predisposition and congenital malformations. "In addition, this individual had an IF in CHEK2 and a mosaic uniparental disomy of the 11P region associated with Beckwith-Wiedemann syndrome." (PMID 40195116, 2025).
breast adenocarcinoma (1 paper, 2022). "Family history revealed one cousin with breast adenocarcinoma with the same CHEK2 mutation and her daughter was found to be a CHEK2 mutation carrier." (PMID 36061833, 2022).
chromophobe renal cell carcinoma (1 paper, 2023). Chromophobe renal cell carcinoma is a rare subtype of renal cell carcinoma, originating from the intercalating cells of the collecting ducts and macroscopically manifesting as a well-circumscribed, highly lobulated, solid tumor that is usually diagnosed at an early stage. "All tumors except for chromophobe renal cell carcinoma (KICH) showed elevated levels of CHEK2 expression compared to normal cells." (PMID 38081888, 2023).
chronic myeloid leukemia (1 paper, 2023). "The proband has five siblings, including one who is a carrier of the variant in CHEK2 and has had chronic myeloid leukemia since age 65, three siblings who are carriers of the variant and are currently healthy collaterals, and only one who has not inherited the variant." (PMID 38136276, 2023).
desmoid tumor (1 paper, 2024). A desmoid tumor (DT) is a benign, locally invasive soft tissue tumor associated with a high recurrence rate but with no metastatic potential. "In a small series of patients with desmoid tumors, disease-causing variants were identified in CHEK2, ERCC5, BLM, MSH6, and PALB2; however, none of these genes has been shown to be associated with increased risk of having desmoids." (PMID 38540414, 2024).
Down syndrome (1 paper, 2021).
embryonal sarcoma of the (1 paper, 2024).
embryonal sarcoma of the liver (1 paper, 2024).
endocrine neoplasias (1 paper, 2022). "Future studies with other patients and families will be instructive to assess whether CHEK2 variants may have any impact as a potential modifier in endocrine neoplasias." (PMID 36440216, 2022). "Here we report that both sisters have a germline CHEK2 mutation, and in at least one of the tumors, a somatic mutation that may be the driver for their endocrine neoplasias was identified in the NF1 gene." (PMID 36440216, 2022).
endometrial ovarian cancer (1 paper, 2024).
germinoma (1 paper, 2010). A malignant germ cell tumor arising in the central nervous system. "Genes CHEK2 and HUS1, which are involved in the DNA damage checkpoint, were significantly overexpressed in germinomas (p = 3.45*10e-2)." (PMID 20178649, 2010).
giant cell glioblastoma (1 paper, 2024). "In conclusion, we present a rare case of giant cell glioblastoma with an inherited germline CHEK2 mutation." (PMID 39411129, 2024). "This represents the first reported case of a CHEK2 germline mutation in giant cell glioblastoma, further supporting the significance of impaired DNA repair mechanisms in the development of this disease." (PMID 39411129, 2024). "In addition to the germline CHEK2 mutation, the giant cell glioblastoma exhibited a genome-wide loss of heterozygosity, a characteristic observed in a subset of giant cell glioblastomas." (PMID 39411129, 2024).
HIV-1 infection (1 paper, 2018). The type species of lentivirus and the etiologic agent of acquired immunodeficiency syndrome (AIDS). "Inhibitors of CHEK2, CSNK2A1, and CDK2 did not significantly reduce CCR5-tropic HIV-1 infection but inhibited CXCR4-tropic HIV-1 at one or more concentrations." (PMID 29970186, 2018).
insular carcinoma (1 paper, 2021). "In this study, we prioritized three potentially deleterious coding variants in three genes, namely CHEK2, TIAM1, and EWSR1 in an NMTC family with aggregation of PTC, micro-PTC, and insular carcinoma." (PMID 33692755, 2021).
insulinomas (1 paper, 2017).
intestinal polyp (1 paper, 2023). Discrete abnormal tissue masses that protrude into the lumen of the intestine. "We present the first known case of a child carrying a germline and somatic pathogenic variant of PTEN associated with a germline and somatic variant of CHEK2, with a phenotype characterized by macrocephaly, DD, skin lesions, and very early onset of MB SHH and intestinal polyps." (PMID 37692099, 2023).
intestinal polyposis (1 paper, 2023). "We report the exceptional case of an infant carrying a germline and somatic pathogenic variant of PTEN and a germline and somatic pathogenic variant of CHEK2 who developed a MB SHH in addition to intestinal polyposis." (PMID 37692099, 2023).
invasive lobular carcinoma (1 paper, 2024). "In one case (patient 26), an additional somatic missense CHEK2 mutation (p.K373E) was identified in an invasive lobular carcinoma (ILC) arising in a 70-year-old germline CHEK2 exon 9 deletion carrier." (PMID 38091153, 2024).
liver sarcoma (1 paper, 2024). A malignant soft tissue neoplasm that arises from the liver.
lobular carcinoma (1 paper, 2013). "Additionally, an association of the CHEK2 p.I157T missense mutation has been reported with lobular carcinoma." (PMID 23806170, 2013).
lung neoplasm (1 paper, 2020). A benign or malignant, primary or metastatic neoplasm involving the lungs. "For instance, SF(Pkinase, Death) contains seven members (MAP3K8, MAPK3, MAPK14, MAPK1, AKT1, CHEK2, and DAPK1) that are related to lung neoplasms." (PMID 31937869, 2020).
mesenchymal tumors (1 paper, 2024). "For instance, the risk of mesenchymal tumors in CHEK2 c.1100delC carriers is not known." (PMID 39594770, 2024).
neuroendocrine carcinoma (1 paper, 2025). A malignant neuroendocrine neoplasm composed of cells containing secretory granules that stain positive for NSE and chromogranin. "CHEK2, a tumor suppressor gene that plays a crucial role in DNA damage response, has been identified in some case reports in neuroendocrine carcinoma and small cell carcinoma but has not been studied in association with outcomes in this population." (PMID 39858006, 2025).
neuroendocrine tumors (1 paper, 2021). "A recent whole-genome sequencing study of pancreas neuroendocrine tumors suggested that sporadic neuroendocrine tumors contain an elevated proportion of germline mutations in the DNA repair genes MUTYH, CHEK2, and BRCA226." (PMID 34031376, 2021).
Noonan syndrome (1 paper, 2024). Noonan Syndrome (NS) is characterized by short stature, typical facial dysmorphism and congenital heart defects. "Germline alterations included variants associated with cancer predisposition syndromes, such as CHEK2 and Noonan syndrome (PTPN11)." (PMID 39687881, 2024).
oesophageal adenocarcinomas (1 paper, 2004). "We found CHEK2*1100delC in 0.5% of 190 oesophageal squamous cell carcinomas and in 1.5% of 196 oesophageal adenocarcinomas." (PMID 14970869, 2004).
pancreatic ductal adenocarcinoma (1 paper, 2025). An infiltrating adenocarcinoma that arises from the epithelial cells of the pancreas. "However, one study has demonstrated that irinotecan-containing therapy improves PFS more than other treatment regimens in patients with pancreatic ductal adenocarcinoma harboring CHEK2/ATM mutations (germline/somatic)." (PMID 39858006, 2025).
pediatric tumors (1 paper, 2023). "The CHEK2 gene is one of the well-known CPGs, with variants associated with the occurrence of different types of pediatric tumors." (PMID 38139220, 2023).